TNF (tumor necrosis factor)
Diseases named in the same sentence as TNF in open-access papers (continued):
Sharing a sentence is not in itself a finding about the gene and the disease.
Obesity (continued). "The development of IR in T2DM and obesity is influenced by both resistin and TNF-α." (PMID 33456608, 2020). "Moreover, other obesity-induced inflammatory mediators such as TNFα, IL-1 family, and IL-6 have also exhibited the ability to promote insulin resistance." (PMID 32971975, 2020). "Numerous data indicate that TNFα levels increase along with the severity of obesity." (PMID 32443588, 2020). "EPA and DHA containing Ω-3 PUFAs have anti-obesity, anti-insulin resistance and anti-inflammatory functions by enhance insulin sensitivity due to declining inflammatory cytokines including tumor necrosis factor, interlukin-6 and enhancing emission of anti-inflammatory adiponectin." (PMID 32928224, 2020). "Tumor necrosis factor (TNF) is an adipokine that is elevated in states of obesity and inflammation." (PMID 31912874, 2020). "In adipose tissue, AREG expression is markedly upregulated during HFD-induced obesity in wild type mice but is profoundly downregulated in iRhom2-deficient mice, suggesting a possibly leading role of EGFR-dependent cellular processes over TNF in the modulation of metabolic pathways during obesity." (PMID 33330676, 2020). "However, Chu and Li32 concluded that the increases in TNF-α and IL-6 are mainly influenced by the obesity factor." (PMID 30213594, 2020). "TNF-α and IL-6 have pleiotropic effects including regulation of lung inflammation, lipolysis, and skeletal muscle atrophy, and IL-6 knockout mice develop obesity." (PMID 31665000, 2019). "However, adipose tissue and muscle also act as endocrine organs that release various cytokines, such as leptin, adiponectin, tumor necrosis factor-alpha, and interleukin-6, and alter insulin sensitivity in obesity and metabolic syndrome." (PMID 31470507, 2019). "TNF-α may play important roles in inflammatory catabolic states, such as obesity and insulin resistance, because it is responsible for the increase in gluconeogenesis, loss of adipose tissue, and proteolysis." (PMID 30717377, 2019). "Previous studies have demonstrated a relationship between inflammatory biomarkers such as Interleukin (IL)-6, IL-18, and IL-10, tumor necrosis factor alpha (TNF-alpha), and interferon gamma with chronic diseases, mental disorders, and obesity and overweight, as well as self-rated health." (PMID 30728031, 2019). "In particular, pro-inflammatory macrophage accumulation in adipose tissue is an important feature of obesity, correlating with local expression of inflammatory markers including tumor necrosis factor-α (TNF-α), interleukin-6 (IL-6), interleukin-1β (IL-1β) and C-C Motif Chemokine Ligand 2 (CCL2)." (PMID 31443599, 2019). "Given that accumulating evidence points to the co-existence of increased circulatory levels of TNF-α, palmitate and CCL4 in obesity/T2D, we asked whether TNF-α and palmitate could cooperatively trigger the CCL4 production in human monocytic cells." (PMID 31546972, 2019). "Loss of TG2 did not affect the obesity-related alterations in the expression levels of the adiponectin and resistin, but obesity-induced expressions of TNF-α, MCP-1, and leptin were significantly enhanced in the gWAT adipocytes of TG2 null animals as compared to wild type mice." (PMID 31165747, 2019). "Inflammation in obesity is marked by an increase in TNF and hsCRP." (PMID 33708303, 2019). "The adipokines leptin, resistin, and TNF-α are also involved in glucose metabolism, but unlike adiponectin, their elevated levels are associated with the development of diabetes and obesity." (PMID 31514360, 2019). "Furthermore, JNK pathway is activated by TNF-α stimulation and has been regarded as a crucial mediator of obesity and insulin resistance." (PMID 31470850, 2019). "Leptin, as a well-known obesity marker, enhances the production of TNF and IL-6 in monocytes." (PMID 31208019, 2019).
Obesity (continued). "A similar effect was observed in TNF-α and interleukin-10, suggesting that genetic variants in adipokines do not have a significant effect in Mexican-Mestizo children obesity." (PMID 31354816, 2019). "Moreover, the finding two decades ago that proinflammatory cytokines like tumor necrosis factor-α (TNF-α), among others, are overexpressed in adipose tissue of obese mice provided a relation between obesity, diabetes and chronic inflammation." (PMID 31126031, 2019). "Despite the evidence linking anti-TNF strategies with the improvement of insulin sensitivity, it is not known how the selective neutralization of solTNF signaling can impact the deleterious metabolic-immune interactions present in obesity that affects IR." (PMID 31892368, 2019). "Obesity, type 2 diabetes, mtDNA, cytokines, TNF-a, chemerin." (PMID 30871547, 2019). "Moreover, in the experimental setting of obesity, a 1-h infusion of propofol resulted in increased airway resistance, atelectasis, and pulmonary inflammation mediated by increased TNF-α and IL-6 in lung tissue, with depletion of antioxidative enzymes." (PMID 31138279, 2019). "Also, 22:6n3 (DHA) was positively correlated with TNF-α (β = 0.31, R2 = 0.39, p = 0.05) in women with overweight and obesity." (PMID 31141526, 2019). "Additionally, LPS has been repeatedly shown to positively related to obesity and especially adipocytokines, such as SC-LCBs-increased adiponectin, and decreased leptin, resistin, and TNF-α." (PMID 31374958, 2019). "High-fat-diet (HFD)-induced obesity may also induce increased levels of IL-1β, tumor necrosis factor (TNF)-α, IL-17, and transforming growth factor (TGF)-β in lung tissue." (PMID 31133649, 2019). "TNF is increased in obesity and it contributes to insulin resistance." (PMID 30841637, 2019). "Furthermore, obesity-derived processes promote the release of pro-inflammatory cytokines, such as tumor necrosis factor (TNF), that stimulate ceramide synthesis and contribute to NAFLD progression." (PMID 31861664, 2019). "The first molecular link between inflammation and obesity is TNF-α." (PMID 31597283, 2019). "Overall, these studies report that adherence to a Mediterranean Diet and/or calorie restriction were associated with decreased DNA methylation in obesity-related genes such as PDK4, KCNQ1, WT1, SH2B1, FTO, BDNF, and PPARGC1A or inflammatory genes such as TNF-α." (PMID 31506096, 2019). "Classical obesity-induced pro-inflammatory cytokines, which mainly originate from immune cells and include TNF-α, IL-6, and TGF-β, participate in tumor cell proliferation and invasion, and may subsequently contribute to tumor progression." (PMID 31379820, 2019). "However, ABG treatment attenuated the obesity-induced increase in the gene expression of IL-1β (p < 0.01), TNF-α (p < 0.05) and iNOS (p < 0.01)." (PMID 30642033, 2019). "Obesity-induced skeletal muscle inflammation, characterized by increased levels of inflammatory cytokines such as tumor necrosis factor α (TNFα) and interleukin-6 (IL-6), promotes an imbalance in muscle protein synthesis and degradation leading to muscle atrophy." (PMID 31312114, 2019). "With regard to the relation between TNF-α and obesity, plasma concentration of TNF-α and its receptors were found to be higher in obese individuals, which may get alleviated with weight loss." (PMID 31420057, 2019). "Taking our findings into consideration, we surmise that the co-presence of TNF-α and FFAs in obesity may enhance IL-8 production, thereby contributing to macrophage recruitment into the adipose tissue and metabolic inflammation." (PMID 31443599, 2019). "In addition, interaction between endogenous TAK1 and TAB1 was strongly inhibited in the liver of FGF-1 treated obesity- or TNF-α-induced insulin resistance mice." (PMID 31866871, 2019). "Higher perilipin activity and higher TNF-α levels are observed in obesity." (PMID 31133986, 2019). "The elevated TNF-α levels have been reported in obesity and other insulin-resistant states." (PMID 30863203, 2019).
Obesity (continued). "In obesity, many proinflammatory immune cells, including M1 macrophages and Th1 cells, infiltrate and accumulate in muscle tissues, which secrete proinflammatory cytokines, such as TNF-α, IL-1β, and MCP1." (PMID 31582899, 2019). "Inflammatory cytokines appear to play a key role in linking obesity and colorectal carcinogenesis particularly so for IL-6 and tumor necrosis factor-α; a recent study also describing IL-13 as a potential factor involved in the development of obesity-related colon cancer onset." (PMID 31906216, 2019). "In addition, vitamin D acts as an immune-suppressor of inflammatory markers, including tumor necrosis factor-alfa (TNF-α) and interleukin (IL)-6, both of which are characteristically elevated in subjects with obesity." (PMID 31362440, 2019). "Increased TNFα concentration strongly indicates the involvement of inflammatory process in obesity." (PMID 31737129, 2019). "Thus, among overexpressed pathways common to both tumor and mucosa, we found the mammalian target of rapamycin (mTOR), AMP‐activated kinase (AMPK), and tumor necrosis factor (TNF) signaling, already proposed to link diabetes, obesity, and cancer." (PMID 30628165, 2019). "Obesity is a chronic low-grade inflammation process; thus the cytokines and other inflammatory markers produced by over-loading adipose tissue, such as interleukin-1 (IL-1), IL-6, and tumor necrosis factor alpha (TNF-alpha), will be increased." (PMID 31681268, 2019). "Obesity can promote adipocytes to secrete pro-inflammatory factors, such as TNF-α, IL-6, and IL-18." (PMID 31440472, 2019). "TNF has a critical role in obesity-induced insulin resistance, in addition to its other functions." (PMID 31514326, 2019). "Obesity leads to the polarization of macrophages from the M2 to the M1 phenotype in fat tissues and aggravate inflammation in the fat tissue by increasing the proportion of M1 macrophages which secrete pro-inflammatory cytokines such as TNF-α and IL-1β." (PMID 31731817, 2019). "In obesity, it has been found that a shift in the activation state of macrophages in AT from M2Ф in lean animals to M1Ф, upon the activation of MФ, secretes numerous cytokines and chemokines, such as TNF-α, IL-1, IL-6 and chemokine MCP-1." (PMID 31357412, 2019). "A meta-analysis of the influence of adipokine polymorphisms in adipokine genes (LEP, ADIPOQ, IL-1β, IL-6, and TNF-α) in obesity susceptibility showed that there was not association with the risk of obesity and LEP variants in adults." (PMID 31354816, 2019). "Furthermore, elevated concentrations of IL-6, TNF-α, IL-10, and IFN-γ were associated with overweight and obesity (BMI above 25)." (PMID 31139232, 2019). "In fact, obesity has been associated with elevated levels of proinflammatory markers such as interleukins, C reactive protein (CRP), interferon (IFN)-γ, and tumor necrosis factor (TNF)-α." (PMID 31137906, 2019). "Obesity is associated to a low-grade inflammation that alters the expression of adiponectin, leptin, IL-6, Monocyte Chemotactic Protein 1 (MCP1), TRAIL, LIGHT/TNFSF14, OPG, and TNFα." (PMID 31130918, 2019). "However, in case of obesity the secreted adipokines take on a more proinflammatory profile, secreting IL-6, TNFα and leptin, as well as resistin and visfatin." (PMID 30787925, 2019). "Bifidobacterium may exert multiple positive effects on human health ranging from prevention of obesity and infections to resolution of ulcerative colitis via the down regulation of TNF-α and IL-1." (PMID 31123874, 2019). "In obesity-associated metabolic inflammation, FFAs may act as ligands for TLR4 and thus induce TNF-α production by monocytes/macrophages, which suggests pathological interactions between FFAs and TLR4." (PMID 31443599, 2019). "Reportedly, TNF-α contributes to the increased TGF-β expression during obesity." (PMID 31622373, 2019).
Obesity (continued). "It has been suggested that obesity-related inflammatory cytokines, including tumor necrosis factor α (TNFα), interleukin-1β (IL-1β) and IL-6, may accelerate muscle catabolism." (PMID 29949600, 2018). "Although some cytokines such as TNFα and IL1β reduce adipose Lipin-1 expression, the mechanism by which the expression of Lipin-1 was impaired in adipose tissue in obesity states remains unclear." (PMID 29534036, 2018). "In addition, in this 3D model, the expression of TNFα was increased, in case of obesity, and a positive correlation was highlighted between genes coding for inflammatory proteins such as IL-6 and TNFα." (PMID 29389973, 2018). "The adverse impact of obesity upon the periodontium could be mediated by proinflammatory cytokines such as interleukins (IL-1, IL-6 and TNF-α), and an inverse relationship has been reported with antioxidants." (PMID 29680852, 2018). "The anti-obesity action of chronic NP-1 administration might be mediated by TNFα, which is known to have anorectic actions in the hypothalamus and to regulate both Dmnt1 and Ucp1 expression in adipose tissues." (PMID 29959379, 2018). "Interestingly, ablation of TNF signaling in mice by genetic deletion of the type 1 TNF receptor (Tnfr1−/−) markedly impedes the development of obesity‐dependent liver cancer." (PMID 29706024, 2018). "Markers of inflammation, such as tumor necrosis factor alpha (TNF-α), interleukin-6 (IL-6), CRP and MCP-1, are increased in peripheral blood levels in obesity and are associated with IR and may predict the development of type 2 diabetes." (PMID 29694633, 2018). "Obesity is characterized by latent inflammation shown by increased TNFα levels." (PMID 30333974, 2018). "In our study, we reported that obesity sensitized acid saline-induced TNF-α production in the DRG." (PMID 29444083, 2018). "Moreover, as occurs in peripheral tissues in obesity and type 2 diabetes, proinflammatory cytokines, in particular TNFα, mediate the development of neuronal insulin resistance." (PMID 30692905, 2018). "A large body of work has shown that excess adipose tissue induces adipocyte dysfunction that further causes an imbalance of the production of adipokines such as tumor necrosis factor alpha (TNF-α) or IL-6 involved in the onset of IR and other obesity associated disturbances." (PMID 30200422, 2018). "Importantly, adequate evidence has shown that tumor necrosis factor alpha (TNF-α) plays a critical role in obesity." (PMID 29444083, 2018). "TNFα expression has been shown to be increased in obesity, arthritis, and osteoporosis." (PMID 30333974, 2018). "Like TNFα, the levels of IL-6 in plasma increase with fat mass and obesity." (PMID 30366378, 2018). "Human adipose tissue secretes TNF-α, which may be a good explanation of the relation between obesity and inflammation." (PMID 30518097, 2018). "Using TNF−/− male mice as a model of reduced systemic inflammation, we demonstrated that despite diet‐induced obesity in TNF−/− mice there was a reduction in circulating Ly6Chigh inflammatory monocytes and macrophage accumulation in adipose tissue in comparison to WT mice." (PMID 30548217, 2018). "While the negative impact of obesity in patients with psoriasis is well-known, our observations that obesity uniformly results in inferior response to anti-TNF therapy across all rheumatic diseases that we studied has important implications for both clinical practice and clinical trial design." (PMID 29771924, 2018). "Studies have shown that saturated fatty acid rich-diets, besides inducing obesity, are able to increase blood glucose levels due to the suppression of insulin signaling by TNFα and other inflammatory cytokines, as well as the excess FA, triggering insulin resistance." (PMID 29320433, 2018). "The first molecular link identified between obesity and inflammation was TNF-α." (PMID 30360409, 2018).
Obesity (continued). "Landmark studies showed that pro-inflammatory factors, such as tumor necrosis factor α (TNFα), are elevated systemically and locally within the adipose tissue of murine models of obesity and diabetes, and contribute directly to obesity-induced insulin resistance." (PMID 29570618, 2018). "Additionally, TNF-α is a pro-inflammatory cytokine that is closely tied to the pathogenesis of obesity and insulin-resistance." (PMID 29922174, 2018). "Additionally, elevation of TNFα, a proinflammatory cytokine, has been widely accepted as an important mechanistic connection between obesity and its complications." (PMID 29615900, 2018). "Furthermore, IL-6 and TNF-α promoted the inflammatory phenotype of adipocytes, providing a link between low-grade inflammation, obesity, insulin resistance, and T2D." (PMID 30524198, 2018). "Activation of TLR4 by saturated fatty acids elicits, through the activation of NFκB, the secretion of several proinflammatory cytokines such as TNF-α, IL-6, and MCP-1, which are involved in the development of obesity-associated inflammation and insulin resistance." (PMID 30116154, 2018). "TNF-α was identified as an early potential target in the treatment of IR in obesity." (PMID 28661198, 2018). "Therefore, our data show that TNF is a key regulator of diet‐induced changes to monocyte/macrophage‐driven inflammation in obesity, and that TNF can contribute to metaflammation in a manner that is independent of adipocyte hypotrophy and regulation of glucose." (PMID 30548217, 2018). "According to the literature, the adipose tissue in obesity is characterized by increased production and secretion of inflammatory molecules, such as TNF-α and IL-6, which may have local and systemic effects." (PMID 30020947, 2018). "There are no records in the literature of such alterations with the use of this type of diet, especially when it refers to changes in the intestinal epithelium in a state of obesity, which are possibly related to the increase in TNF-α, as already well established in the literature." (PMID 29950343, 2018). "Indeed, many reports have demonstrated the linkage between the increased production of inflammatory cytokines, such as TNF-α, IL-6 and certain adipokines, during the inflammatory process in obesity and the development of insulin resistance." (PMID 30914847, 2018). "Expression of TNF-α and infiltration of macrophages in adipose tissue are more pronounced in obese than in non-obese individuals, and expression changes are reduced with the improvement of obesity." (PMID 30301191, 2018). "In conclusion, obesity is associated with inferior response to anti-TNF therapy in patients with rheumatic diseases, but not in patients with IBD." (PMID 29771924, 2018). "Obesity increases systemic levels of tumor necrosis factor α (TNFα) and interleukin-6 (IL-6)." (PMID 30591653, 2018). "Therefore, TNFα is a potential contributor to vascular insulin resistance in elderly people and/or people suffering from obesity." (PMID 29464018, 2018). "Although all mechanisms underlying the link between obesity and IR are not entirely clear, it is known that hormones and cytokines such as resistin, tumor necrosis factor (TNF-α), and interleukin-6 (IL-6) secreted by adipocytes unbalance the action of insulin." (PMID 30513771, 2018). "First, we observed that obesity was associated with a 60% higher odds of failing anti-TNF therapy as compared to non-obese and normal BMI counterparts, for most IMIDs, including RA, spondyloarthropathies and psoriasis and psoriatic arthritis, but not IBD." (PMID 29771924, 2018). "In addition, increased TNF‐α in the glomerulus can induce albuminuria after 2 months of obesity in ZF rats." (PMID 29632818, 2018). "Surprisingly, we did not detect any major effect of injury and obesity on the expression levels of TNF or the associated genes Bcl3, Errfi1, Irak3, Myd88, and Thbs1 in our obese model." (PMID 29922174, 2018).